SNORA19 (small nucleolar RNA, H/ACA box 19)
Synonyms: ACA19
Gene: Small nucleolar RNA gene on chromosome 10 (119,060,011 to 119,060,138, reverse strand). Ensembl gene ENSG00000207468.
Gene Ontology:
Biological process: RNA processing
Cellular component: nucleolus
Homologues: Orthologues: chimpanzee SNORA19 (100% identical), macaque SNORA19 (97% identical), guinea pig SNORA19 (95% identical), mouse Gm54426 (92% identical), mouse Snora19 (92% identical), rabbit SNORA19 (92% identical), rat LOC120093054 (91% identical), pig SNORA19 (91% identical), rat Snora19 (74% identical), rat AABR07048648.1 (59% identical).
Diseases named in the same sentence as SNORA19 in open-access papers:
SNORA19 is named in the same sentence as 2 diseases in open-access papers, as found by Europe PMC text mining. Sharing a sentence is not in itself a finding about the gene and the disease. The quoted sentences say what the papers report.
ovarian carcinoma (1 paper, 2022). A malignant neoplasm originating from the surface ovarian epithelium. "Interestingly, the knockdown of two examples of these HGSC-associated snoRNAs, SNORA81 and SNORA19, inhibited the proliferation and induced apoptosis of three different model ovarian cancer cell lines consistent with their upregulation in the aggressive HGSC." (PMID 35047824, 2022). "To understand the mechanism by which SNORA19 and SNORA81 affect cell growth we examined the impact of their knockdown on cell survival and proliferation rate, in different ovarian cancer model cell lines featuring different levels of snoRNA expression and rRNA modification." (PMID 35047824, 2022).
SNORA19 also shares sentences with these, for which no sentence is quoted: cancer (1 paper).